EGFR (epidermal growth factor receptor)
Diseases named in the same sentence as EGFR in open-access papers (continued):
Sharing a sentence is not in itself a finding about the gene and the disease.
lung cancer (continued). "With regards to the therapeutic implications of our findings, there have been several studies of anti-estrogen therapy in lung cancer particularly looking at EGFR mutated NSCLC." (PMID 37700839, 2023). "In EGFR-mutated lung cancer cycling persisted cells, the shift of metabolism toward FAO was observed upon treatment with tyrosine kinase inhibitor." (PMID 38001865, 2023). "EGFR-mutated lung cancer patients who are former or current smokers have shorter progression free survival (PFS) and overall survival compared to never smokers." (PMID 37653450, 2023). "Activation of MEK/erk pathway can upregulate B7H4, and activation of PI3K/Akt can upregulate PD-L1, suggesting that MEK/erk and PI3K/Akt signaling pathways are involved in EGFR mutation-positive lung cancer." (PMID 36910653, 2023). "EGFR mutations (L858R point mutation and exon 19 deletion) in lung cancer have been well studied and testified to have good effects of EGFR tyrosine kinase inhibitor (TKI) such as gefitinib and erlotinib." (PMID 35822637, 2023). "The expression of PD-L1 can be down-regulated by the EGFR inhibitor erlotinib in lung cancer with EGFR receptor mutation." (PMID 36688087, 2023). "In this population‐based cohort study among patients with early‐stage (I–IIIA) non‐small cell lung cancer in Denmark, nearly half of the patients underwent EGFR gene mutation testing at diagnosis of disease, and 8.9% of the tested patients were EGFRm‐positive." (PMID 35719062, 2023). "One example of genetic differences between races is the mutation frequencies of the EGFR (epidermal growth factor receptor) gene (the typical target in lung cancer therapy) where mutations occur in Asian patients 30% of the time and only 7% in White patients." (PMID 37510451, 2023). "Targeted therapies against receptor tyrosine kinases (RTKs) are currently used with success in cancers displaying clear oncogene addiction, such as in epidermal growth factor receptor (EGFR)‐mutated lung cancers." (PMID 36799689, 2023). "The gene mutation rate of patients with lung cancer presenting EGFR as the main genotype is 30%–40% in Asia and 10%–15% in Europe among the Caucasian population." (PMID 37124493, 2023). "Overexpression of AXL has been found in EGFR-mutated lung cancer models that acquired resistance to the first-, second- or third-generation TKIs." (PMID 37894376, 2023). "One patient with EGFR L858R–variant lung cancer received chemoradiotherapy after multidisciplinary team review." (PMID 37490292, 2023). "Since the discovery of epidermal growth factor receptor (EGFR) mutations in lung cancer patients, the development of EGFR tyrosine kinase inhibitors (EGFR-TKIs) has increased the survival of patients with EGFR-mutant non-small cell lung cancer (NSCLC)." (PMID 37221285, 2023). "Genomic changes in EGFR kinase domains, discovered after extracellular domain mutations, were shown to be much more significant and frequent in lung cancer formation, notably in NSCLC." (PMID 37754880, 2023). "As our understanding of the molecular biology of lung cancer increases, many mutated targets are being identified, including the epidermal growth factor receptor (EGFR), anaplastic lymphoma kinase, ROS1, BRAF V600E mutation, etc." (PMID 36716088, 2023). "Though our finding is contrary to what is found in most studies on EGFR-mutated lung cancer, it is similar to a study on 310 lung cancer patients, which noted a protective effect of EGFR-mutated patients on DVT risk." (PMID 37232831, 2023).
lung cancer (continued). "Adenocarcinoma is the most common type of lung cancer, and the frequency of EGFR mutation‐positive lung cancer is particularly high among the Asian population." (PMID 36578073, 2023). "It is well known that the EGFR gene is often mutated in numerous carcinoma, such as breast cancer, lung cancer and colon–rectal cancer." (PMID 37046732, 2023). "First- and second-generation EGFR-TKIs are effective in most cases of lung cancer harboring EGFR driver mutations." (PMID 37841421, 2023). "We also demonstrated that MET inhibitors can overcome HGF‐induced resistance to EGFR tyrosine kinase inhibitors (TKIs) in EGFR‐mutated lung cancer cell lines." (PMID 36416133, 2023). "Various short deletions in exon 19 (Del19), along with L858R, a point mutation in exon 21, represent 85–90% of all known EGFR mutations in lung cancer." (PMID 37894376, 2023). "The discovery of activating epidermal growth factor receptor (EGFR) mutations as the first targeted and predictive oncogenic driver change in lung cancer has profoundly changed the diagnosis and therapeutic landscape of lung AC." (PMID 37446385, 2023). "LASSBio-1920 showed promising cytotoxic potential and high selectivity for colon cancer cells (HCT-116) and lung cancer cells overexpressing mutated EGFR (PC-9)." (PMID 37111767, 2023). "TIDE and TMB analyses also showed that rare EGFR variants was more likely to respond to PD-L1/PD-1 inhibitors than wild-type, L858R-mutated, and exon 19 deletion-mutated EGFR lung cancers." (PMID 37033978, 2023). "EGFR gene mutation can occur in many epithelial tumors, among which the incidence in lung cancer is significantly higher than that in other tumor types, reaching 30.6%, followed by brain tumors and esophageal cancer." (PMID 36701708, 2023). "Gefitinib is another EGFR-tyrosine kinase inhibitor implicated against liver and lung cancers and it has exhibited its efficacy in mitigating the breast cancer cell proliferation of MCF-7 and BT-474." (PMID 37910519, 2023). "Lung cancer is driven by different molecular alterations, including the epidermal growth factor receptor (EGFR) mutations and the rearrangements of the anaplastic lymphoma kinase (ALK) and the c-ros1 (ROS1) genes." (PMID 37340403, 2023). "A third generation of anti-EGFR drugs has been developed to overcome this resistance in lung cancer with the T790M variant, including osimertinib." (PMID 37007070, 2023). "Second, the EGFR mutation status was investigated only in one lung cancer type (adenocarcinoma); thus, further studies in other lung cancer types are warranted." (PMID 37185611, 2023). "A variety of intracellular molecules are also DTP inducers in EGFR-mutated lung cancers, including Aurora kinase A, ERK, NF-kB, STAT3, and β-catenin." (PMID 37920509, 2023). "FDA-approved drugs like osimertinib and crizotinib specifically inhibit these aberrant pathways, providing remarkable benefits in patients with EGFR-mutated or ALK-positive lung cancer." (PMID 37686423, 2023). "Dysregulation of receptor tyrosine kinase (RTK) signaling leads to lung cancer, such as activating EGFR mutations are present in 15% of NSCLC, BRAF and KRAS always also mutated in lung cancer." (PMID 37061730, 2023). "Epidermal growth factor receptor (EGFR) gene mutations are key factors in the development of non‐small cell lung cancer (NSCLC), with an incidence of 40%–60% in Asian populations." (PMID 37723846, 2023). "In early-stage lung cancer, liquid biopsy has become an increasingly important method for detecting specific mutations in tumor DNA, such as EGFR mutation." (PMID 37373532, 2023). "Drugs that target specific EGFR mutations have significantly extended the survival of lung cancer patients." (PMID 36770773, 2023). "Liquid biopsy of circulating tumor DNA (ctDNA) for lung cancer is a less invasive method than conventional tissue biopsy for identifying EGFR gene mutations." (PMID 38304031, 2023).
lung cancer (continued). "Considering the age of individuals at high risk for lung cancer, the incidence of EGFR mutation in patients aged 40 and older was higher than that in those under age 40 (P < 0.001)." (PMID 37924162, 2023). "Unfortunately, after a year, the patients become resistant to erlotinib or gefitinib due to further lung cancer mutations, such as T790M EGFR." (PMID 37508387, 2023). "With this approach, it has been demonstrated that the epidermal growth factor receptor (EGFR) plays an important role in the diagnosis and follow-up of lung cancer, and that mutations in the EGFR gene can be used as biomarkers." (PMID 38304031, 2023). "Lung cancer cells harboring an EGFR T790M mutation, such as H1975, are specifically targeted by the third‐generation EGFR TKI AZD." (PMID 37013960, 2023). "The results showed that in EGFR mutation-positive lung cancer, not only the density and function of CD8+ tumor-infiltrating lymphocytes are suppressed, the PD-L1 genes CD274 and CD86 are also downregulated, and HHLA2 and VTCN1 (B7-H4) were upregulated." (PMID 36910653, 2023). "EGFR gene mutation is a form of the gene variant that frequently occurs in lung cancer, resulting in an overactivated EGF signal that stimulates abnormal cell growth and tumorigenesis." (PMID 36770773, 2023). "Tyrosine kinase inhibitors (TKIs) targeting epidermal growth factor receptor (EGFR) are effective for many patients with lung cancer with EGFR mutations." (PMID 36647832, 2023). "Objective responses of lung cancer to EGFR tyrosine kinase inhibitors (TKIs) are significantly associated with mutations in EGFR exons 18–21." (PMID 37766136, 2023). "Regarding the characteristics of lung cancer, EGFR or ALK mutations and smoking history were similar between the two groups (45.5% vs. 31.8%, p = 0.353 for mutations; 13.0 ± 20.0 vs. 13.3 ± 19.9 pack-year, p = 0.958 for smoking)." (PMID 37510797, 2023). "In this regard, IGF1R is crucial for the establishment of DTPs following treatment of EGFR-mutated lung cancer cells with an EGFR-specific TKI." (PMID 37894376, 2023). "NSCLC constitutes the major part (approximately 75%) of lung cancer and the overexpression of EGFR in this cancer has been associated with drug resistance and a decreased survival rate." (PMID 38273823, 2023). "Focusing on EGFR-driven lung cancer, which is more common in never-smokers or light smokers, we found a significant association between PM2.5 levels and the incidence of lung cancer for 32,957 EGFR driven lung cancer cases in four within-country cohorts." (PMID 37020004, 2023). "The aim of this review is to describe the epidemiology and clinical features of lung cancer patients affected by uncommon EGFR mutations, and discuss available data on the outcome of patients receiving different treatment options." (PMID 37240224, 2023). "Lung cancers with EGFR gene mutations treated with targeted therapy often develop another genetic change (T790M) that allows them to be treated with a further targeted therapy, Osimertinib, with good outcomes." (PMID 37894366, 2023). "In lung cancer, the discovery of driver mutations in genes, such as the epidermal growth factor receptor (EGFR) and anaplastic lymphoma kinase (ALK), has been transformative." (PMID 37686423, 2023). "EGFR mutations are seen in around 10% of lung cancers in the United States, compared to 35% among East Asians." (PMID 36851259, 2023). "The mutation rate of the EGFR gene in patients with lung cancer is approximately 15% in Europe and the United States, while the probability of this mutation in China is 50% or higher 55-57." (PMID 36619220, 2023).
lung cancer (continued). "Blockade of TNFα signaling can render lung cancer PDXs that express wild-type EGFR sensitive to the treatment of EGFR inhibitors, and improve the therapeutic effect of EGFR inhibitors in lung cancer PDXs with EGFR mutations." (PMID 36923932, 2023). "This study evaluated 154 patients with recurrent non‐small cell lung cancer (NSCLC) with epidermal growth factor receptor (EGFR) mutation who were prospectively registered at multiple institutions." (PMID 37143400, 2023). "Driver oncogenes such as EGFR in lung cancer somatic mutations possess intense oncogenic potential known as “oncogenic addiction,” leading to significant therapeutic effects from a single molecularly targeted drug." (PMID 36835536, 2023). "Epidermal growth factor receptor (EGFR)-mutant lung cancers are associated with a high risk of developing brain metastases (BM)." (PMID 36845694, 2023). "In preclinical studies, mutations of EGFR correlated with VEGF in lung cancer, as it has been shown that EGFR-mutant NSCLC cells hasten the expression of VEGF more than wild-type NSCLC cells." (PMID 36766867, 2023). "Increasing evidence suggests that elevated WT-EGFR expression not only contributes to the pathogenesis of lung cancer but also associates with acquired EGFR TKIs resistance." (PMID 37813845, 2023). "Lung cancer patients with ALK-rearrangement or EGFR mutations had lowest proportion of PD-L1+/CD8+ tumors and the shortest overall survival." (PMID 36874015, 2023). "Use of tyrosine kinase inhibitors (TKIs) is the standard therapy for epidermal growth factor receptor (EGFR)–mutated non–small cell lung cancer (NSCLC) with brain metastases." (PMID 36753281, 2023). "For example, 10–30% of patients with lung cancer present activating mutations in the epidermal growth factor receptor (EGFR) gene." (PMID 37894376, 2023). "One of such trials (NCT05079022) aims to assess the role of Furmonertinib, a third generation anti-EGFR, in EGFR-mutated radically resected stage I lung cancers, with the mutation being detected trough ctDNA analysis." (PMID 37542343, 2023). "Some EGFR-tyrosine kinase inhibitors (EGFR-TKIs) are effective in treating lung cancer patients with rare gene mutations." (PMID 37989343, 2023). "In the present study, we retrospectively analyzed the clinicopathological characteristics, molecular profiles, and prognostic features of NF1 mutations in EGFR mutant lung cancer patients." (PMID 35702826, 2023). "Considering the relatively high frequency of MET alterations in lung cancers with EGFR mutations, co-targeting EGFR and MET with either a kinase inhibitor or an antibody appears to be a logical therapeutic strategy that is currently being evaluated." (PMID 37894376, 2023). "We identified the most relevant patient‐reported symptomatic adverse events (AEs) to measure in patients with non‐small cell lung cancer (NSCLC) with epidermal growth factor receptor (EGFR) exon 20 insertion mutations." (PMID 36583557, 2023). "Epidermal growth factor receptor-tyrosine kinase inhibitor (EGFR-TKI) treatment prolongs the survival of lung cancer patients harbouring activating EGFR mutations." (PMID 37156816, 2023). "Subtype 2 ‘mezzo-forte’ tumours demonstrated mutations in EGFR, a common mutation found in lung cancers exhibiting faster tumour growth." (PMID 37686122, 2023). "The incidence of anaplastic lymphoma kinase (ALK)-rearranged mutations and epidermal growth factor receptor (EGFR)-rearranged mutations in lung cancer patients is around 5% and 15%, respectively." (PMID 37835467, 2023). "With the development of biomarkers, the treatment of lung cancer has also evolved with the introduction of several lines of TKIs in patients with EGFR, ALK, ROS1, and NTRK mutations." (PMID 37371816, 2023). "One circulating tumor cell NGS assay in early-stage lung cancer patients showed that more than 50% of lung cancer patients presented four common mutations, including Notch1, EGFR, IGF2, and PTCH1." (PMID 36874015, 2023).
lung cancer (continued). "Oncogenic mutations within the EGFR kinase domain are well-established driver mutations in non–small cell lung cancer (NSCLC)." (PMID 36830579, 2023). "Extending previous findings that established associations between air pollution and lung cancer, including in LCINS6, we found an association between the frequency of EGFR mutant lung cancer incidence and increasing PM2.5 levels." (PMID 37020004, 2023). "TAS-116 was also effective against gefitinib-naïve and gefitinib-resistant epidermal growth factor receptor (EGFR)-mutated lung cancer." (PMID 38275722, 2023). "In conclusion, this study presented that BM progression after TKI and EGFR mutation type were specific prognostic factors for EGFR-mutated lung cancer BM." (PMID 37020869, 2023). "The PROTACs were designed using the EGFR inhibitor canertinib and the cereblon ligand pomalidomiden and showed anticancer activity in lung cancer cells with EGFR mutations." (PMID 36678835, 2023). "The advent of tyrosine kinase inhibitors (TKIs) for treating epidermal growth factor receptor (EGFR)-mutated non-small-cell lung cancer (NSCLC) has been a game changer in lung cancer therapy." (PMID 36835536, 2023). "Broadly speaking, Δ746–750 deletion and L858R point mutation in EGFR, which are common pathologic mutations in lung cancer, are found in exons 19 and 21, respectively." (PMID 37377752, 2023). "Among the cohort of 1012 lung cancer patients diagnosed with EGFR mutations, a total of 7 individuals exhibited evidence of small cell lung cancer (SCLC) transformation." (PMID 38188289, 2023). "The prognostic role of EGFR mutation status in early‐stage non‐small cell lung cancer (NSCLC) after surgery is still controversial." (PMID 36653333, 2023). "Further work is warranted to explore the long-term effect of selenite and its combination with TKI on EGFR mutation-positive lung cancer." (PMID 36864513, 2023). "In this study, we trained a deep learning-based algorithm to predict the EGFR mutation status in patients with lung cancer using 18F-FDG PET/CT images from multiple hospitals." (PMID 36300191, 2022). "The gene encoding EGFR plays an oncogenic role in lung cancer, and its mutation and amplification have been commonly recorded." (PMID 36499051, 2022). "Assessing tumor EGFR mutation status is necessary for the proper management of patients with advanced non–small cell lung cancer (NSCLC)." (PMID 36232650, 2022). "EGFR‐T790M mutation is a major mechanism underlying acquired resistance to first‐ and second‐generation EGFR tyrosine kinase inhibitors (EGFR‐TKIs) in lung cancer with mutated EGFR." (PMID 35029047, 2022). "LL-37 has been reported to be linked to EGFR signaling in a variety of cells, including lung cancer, corneal epithelial, and airway epithelial cells." (PMID 35039485, 2022). "Erlotinib treatment in combination with cisplatin showed the potential to inhibit cell growth in an EGFR-mutated lung cancer model." (PMID 36553449, 2022). "Mutations in epidermal growth factor receptor (EGFR) play critical roles in the pathogenesis of non–small cell lung cancer (NSCLC), and they are highly associated with sensitivity to tyrosine kinase inhibitors." (PMID 35984165, 2022). "Increasing evidence revealed the involvement of lncRNAs in EGFR-TKI resistance in lung cancer patients with EGFR mutations." (PMID 35902569, 2022). "First, the interaction between the epidermal growth factor receptor and the S100A family can promote angiogenesis and metastasis in various cancers, while the proportion of EGFR mutations is relatively small in these two types of lung cancers." (PMID 36235175, 2022). "Detecting the mechanisms of this resistance is fundamental in lung cancer research, so we evaluated the presence of EGFR mutations in circulating free DNA in plasma of patients with NSCLC under oncological treatment." (PMID 35884384, 2022).